EWSAT1 (Ewing sarcoma associated transcript 1)
Synonyms: FLJ33768; LINC00277; NCRNA00277; TMEM84
Gene: Long non-coding RNA gene on chromosome 15 (69,066,450 to 69,099,990, forward strand). Ensembl gene ENSG00000212766.
Diseases named in the same sentence as EWSAT1 in open-access papers:
EWSAT1 is named in the same sentence as 18 diseases in open-access papers, as found by Europe PMC text mining. Sharing a sentence is not in itself a finding about the gene and the disease. The quoted sentences say what the papers report.
osteosarcoma (11 papers, 2017 to 2024). A usually aggressive malignant bone-forming mesenchymal neoplasm, predominantly affecting adolescents and young adults. "Recently, long non-coding RNA Ewing sarcoma-associated transcript 1 (EWSAT1) has been described as inductor of osteosarcoma (OS) exerting its function like an sponge-lncRNA by binding to miR-24-3p which in turn recognizes ROCK1 3′UTR and represses its translation." (PMID 35447891, 2022). "It is regulated by lncRNA Ewing-sarcoma associated transcript-1 (EWSAT1) and downregulation of MEG3 in the presence of EWSAT1 leads to proliferation, invasion, and cellular migration of osteosarcoma cells, based on gain- and loss-of-function assays." (PMID 29657304, 2018). "Similarly in osteosarcoma, EWSAT1 sponges miR-24-3p and disrupts the miR-24-3p/ROCK1 axis to promote metastasis." (PMID 34440137, 2021). "Though the identification of this lncRNA’s mechanisms in ES cells is a gap in the existing literature, EWSAT1 has since been found to be upregulated in osteosarcoma, cervical cancer, and colorectal cancer among others, in which its suggested mechanism is as a competing endogenous RNA." (PMID 34440137, 2021).
Ewing sarcoma (9 papers, 2016 to 2022). A small round cell tumor that lacks morphologic, immunohistochemical, and electron microscopic evidence of neuroectodermal differentiation. "The lncRNA Ewing sarcoma-associated transcript 1 (EWSAT1) was originally identified in Ewing sarcoma, and has subsequently been associated with proliferation, migration and metastases as well as overall survival (OS) in several other cancers." (PMID 35455947, 2022). "EWSAT1 (Ewing sarcoma-associated transcript 1) is an lncRNA with oncogenic functions in Ewing's sarcoma and nasopharyngeal carcinoma (NPC)." (PMID 29147648, 2017). "Ewing sarcoma-associated transcript 1 (EWSAT1) is found to facilitate Ewing sarcoma oncogenesis by mediating EWS-FLI1 suppression pathways." (PMID 27833134, 2016). "Long non-coding RNA (lncRNA) Ewing sarcoma associated transcript 1 (EWSAT1) has been identified as an oncogene, and its dysregulation is closed corrected with tumor progression in Ewing sarcoma." (PMID 27816050, 2016). "Long noncoding RNA-227 or lncRNA Ewing Sarcoma-associated transcript 1 (EWSAT1) was the first lncRNA discovered in ES as a result of RNA sequencing analysis." (PMID 34440137, 2021). "The examination of EWSAT1 expression facilitates the development of Ewing sarcoma via the repression of target genes, revealing that it plays an important role in the pathogenesis of Ewing sarcoma." (PMID 30658384, 2019). "Upon further RNA sequencing analysis from primary human Ewing sarcoma tissue, EWSAT1 was found to be critical for gene repression downstream of EWS-FLI." (PMID 28353666, 2017). "It has been reported that knockdown of EWSAT1 decreases soft agar colony growth of Ewing sarcoma cell lines, which indicated that EWSAT1 exerted an essential role on the occurrence, development and progression of malignant tumors." (PMID 27816050, 2016). "EWSAT1, also named LINC00277, was first reported as an oncogenic transcription in Ewing sarcoma." (PMID 33225581, 2021). "Interestingly, there is a marked overlap in hnRNPK-repressed genes and those repressed by EWSAT1, suggesting that hnRNPK and EWSAT1 act together to repress the expression of a subset of target genes in the context of Ewing sarcoma." (PMID 30658384, 2019). "The inhibition of EWSAT1 expression diminished cell viability in human Ewing sarcoma cell lines." (PMID 28353666, 2017). "Ewing sarcoma associated transcript 1 (EWSAT1, LINC00277, NR_026949), a kind of lncRNA located on chromosome 15 between 2 protein-coding genes, NOX5 and GLCE, is found up-expressed and functions an oncogenic role in Ewing sarcoma." (PMID 27816050, 2016).
nasopharyngeal carcinoma (8 papers, 2016 to 2025). A carcinoma arising from the nasopharyngeal epithelium. "Calycosin downregulates Ewing-sarcoma-associated transcript 1 (EWSAT1), which enhances the proliferation of cervical and nasopharyngeal cancer cells by sponging miR-330-5p." (PMID 37190145, 2023). "Highly expressed EWSAT1 in human nasopharyngeal carcinoma tissues and cell lines increases the expression of miR-326/330-5p clusters that target the gene cyclin D1, ultimately regulating NPC development and progression." (PMID 29719633, 2018). "Recently, high-through put analysis reveals that EWSAT1 is also highly expressed in human nasopharyngeal carcinoma (NPC)." (PMID 27816050, 2016). "It's demonstrated that CAL significantly impedes lncRNA EWSAT1 expression in nasopharyngeal carcinoma (NPC), followed by influenced downstream factors and pathways, leading to inhibitory growth." (PMID 31178721, 2019).
ovarian carcinoma (4 papers, 2020 to 2023). A malignant neoplasm originating from the surface ovarian epithelium. "EWSAT1 can contribute to the proliferation and invasion of glioma, promote HCC metastasis, and promote the progression of ovarian cancer." (PMID 37928532, 2023).
colorectal cancer (2 papers, 2021 to 2022). A primary or metastatic malignant neoplasm that affects the colon or rectum. "For example, in colorectal cancer, EWSAT1 sponges miR-326 to upregulate FBXL20 and promote proliferation, migration and invasion." (PMID 34440137, 2021).
glioblastoma (2 papers, 2019 to 2022). The most malignant astrocytic tumor (WHO grade IV). "Results showed that EWSAT1 was significantly increased in cancers like Skin Cutaneous Melanoma (SKCM), Glioblastoma multiforme (GBM), Ovarian serous cystadenocarcinoma (OV), and etc., while it was significantly decreased in Testicular Germ Cell Tumors (TGCT), Brain Lower Grade Glioma (LGG) and etc." (PMID 35286362, 2022).
lymph node metastasis (1 paper, 2021). "Further, we found that elevated EWSAT1 expression was more commonly present in OS tissue specimens with distant metastasis and lymph node metastasis (P < .001)." (PMID 33225581, 2021).
metastasis (1 paper, 2021). The spread or migration of cancer cells from one part of the body (where they first appeared) to another. "In the previous section, we elucidated that high EWSAT1 expression was closely related to distant metastasis and lymph node metastasis." (PMID 33225581, 2021).
cancer (7 papers, 2016 to 2023). A tumor composed of atypical neoplastic, often pleomorphic cells that invade other tissues. "Meta-analysis showed that high expression of lncRNA EWSAT1 was associated with poor overall survival (OS) (HR = 2.10, 95% CI, 1.60–2.75, p < 0.0001) in cancers reported." (PMID 35286362, 2022). "Ewing sarcoma-associated transcript 1 (lncRNA EWSAT1) is reported to have a close relationship with the overall survival in many cancers." (PMID 35286362, 2022). "The aberrant expression in multiple cancers demonstrated that EWSAT1 had a strong association with varies cancers." (PMID 35286362, 2022). "In this meta-analysis, we analyzed 6 studies with HR of OS in 4 different cancers, the overall effect showed that high expression of lncRNA EWSAT1 linked to low OS, which indicated EWSAT1 an oncogene in the cancers involved." (PMID 35286362, 2022). "EWSAT1 was associated with progression in several cancer types, such as ovarian, cervical and colorectal." (PMID 34136413, 2021). "However, LINC00271 and EWSAT1 had already been associated with other cancer types." (PMID 34136413, 2021). "Though in most studies the expression of EWSAT1 was up regulated in cancers, but there also cancers in which it was down regulated." (PMID 35286362, 2022). "And aberrant expression of EWSAT1 was also said to affect the OS of patients in some of the cancers above." (PMID 35286362, 2022). "In summary, high expression of EWSAT1 is associate with poor OS, more metastasis, higher stage of TNM stage in many cancers." (PMID 35286362, 2022). "In general, the results of our meta analysis suggest that lncRNA EWSAT1 acts as an oncogene in many cancers, which relate to low OS, more metastasis, higher stage of TNM stage." (PMID 35286362, 2022). "EWSAT1 has been reported to play a pro-tumor role in a variety of cancers." (PMID 37928532, 2023). "However, more patients of well and moderate differentiation cancers were discovered in EWSAT1 high expression group with OR 2.20, 95% CI 1.02–4.76." (PMID 35286362, 2022). "The expression level of EWSAT1 could be used to predict possible prognosis, imply the progression stage of cancers, indicate a cancer that may exist for early diagnosis, act as a potential biomarker and drug target in treatment." (PMID 35286362, 2022). "The expressions of EWSAT1 were all detected by qRT-PCR with cancer tissues." (PMID 35286362, 2022). "Thereby, this meta-analysis intended to explore the overall effect of aberrant EWSAT1 expression with OS in cancers and bridge gap in knowledge between aberrant expression of EWSAT1 and the prognosis and clinicopathological features of patients in different kinds of cancers." (PMID 35286362, 2022). "Our team measured the expression levels of EWSAT1, AC138696.2, AC021321.1, LINC00601, and LINC01775 in KYSE-30, KYSE-410, and KYSE-520 cancer cell lines and in patient cancer tissues and paracancerous tissues using RT-qPCR." (PMID 37812189, 2023). "Enhanced expression of EWSAT1 has been reported to promote cell growth, invasion and EMT by sponging specific miRNAs in various cancers." (PMID 35455947, 2022).
tumor (6 papers, 2016 to 2023). "EWSAT1's function as an oncogene to facilitate tumor progression was partially attributed to its ability to acting as a ceRNA for miR-326/330-5p clusters, and subsequent to activating of the cyclin D1 signaling pathway in NPC." (PMID 27816050, 2016). "Aberrant expression of EWSAT1 was validated between normal and tumor tissues." (PMID 35286362, 2022). "Therefore, we thought that EWSAT1 would act as a tumour initiator in OS, especially in OS metastasis." (PMID 33225581, 2021). "In this study, we found that six prognostic chemokine-related lncRNAs were expressed at different levels in tumor tissues and paired adjacent normal tissues, including LINC00675, PRG1, ROR1-AS1, ANKRD10-IT1, UCA1, and EWSAT1." (PMID 37081402, 2023).
EWSAT1 also shares sentences with these, for which no sentence is quoted: glioma (2 papers); cervical cancer (1); lung carcinoma (1); non-small cell lung carcinoma (1); omphalocele (1); ovarian serous cystadenocarcinoma (1); Skin Cutaneous Melanoma (1); testicular germ cell tumor (1).